MMP9 (matrix metallopeptidase 9)
Diseases named in the same sentence as MMP9 in open-access papers (continued):
Sharing a sentence is not in itself a finding about the gene and the disease.
tumor (continued). "In 4T1 tumor section specimens, we found that 150 mg/kg decreased MMP-9 to 38.54% compared with 75% in the control group, increased TIMP-1 to 76.04% compared with 31.25% in the control group, and increased TIMP-2 to 66.15% compared with 33.33% in the control group, respectively." (PMID 28088791, 2017). "RNA-seq analysis revealed us MMP9 and many tumor related changed genes might be the candidate targets for the PC4 tumor regulation in 143B." (PMID 28881805, 2017). "Furthermore, the regulatory mechanism of MMP-9 in GE-treated cells was investigated because the migration and invasion of tumor cells is connected with MMP-9 expression through the control of transcription factors AP-1, Sp-1, and NF-κB." (PMID 28187175, 2017). "In addition to ECM, MMP2 and MMP9 can cleave cytokines, growth factors, chemokines and receptors of cytokines involved in tumor progression." (PMID 28620234, 2017). "Isothiocyanates abolished MMP-9 expression and tumor metastasis in vivo." (PMID 28969043, 2017). "MMP‐9 also augments tumour‐derived SCF production in an amplification feedback loop." (PMID 28032353, 2017). "It has been reported that tumor-infiltrating MMP-9-positive neutrophils enhance angiogenesis." (PMID 28505114, 2017). "We next tested the hypothesis that modulation of BDNF in the CAF compartment would profoundly impact MMP-9 activity in the tumor compartment." (PMID 28966935, 2017). "Taking into account that the tumor-promoting TAM phenotype also releases MMP-9, and its coformation with LCN2 may be well suited to promote cancer progression." (PMID 28804221, 2017). "Both MMP-2 and MMP-9 are mainly involved in tumor metastasis." (PMID 27073100, 2017). "Lower expression of MMP-9 was observed in tumor tissue in Min/OPN(+/−) and Min/OPN(−/−) mice." (PMID 28505114, 2017). "Most of the downregulated genes, including SRC, TGFB1, MMP9 are known to promote tumor metastasis." (PMID 28977939, 2017). "Moreover, LY294002 and knockdown of Cyclin D1 or MMP9 remarkably blocked the tumor-promoting activity of NCOA5." (PMID 29296214, 2017). "Besides that MMP-9 activity has been reported to increase in various tumor cells such as human lung, breast, ovarian, gastric cancers, acute myeloid leukemia, and chronic myeloid leukemia." (PMID 28677624, 2017). "In tumor-fibroblast co-cultures, fibroblasts stimulate production of MMP9 by tumor cells." (PMID 28423685, 2017). "Furthermore, gelatin zymography analysis has demonstrated that SIK3 induced expression of tumor metastatic CXCR4 through MMP-9 activation." (PMID 28658303, 2017). "Thus, all three cellular components of the breast TME can contribute to MMP9-driven tumor vascularization." (PMID 28977919, 2017). "Furthermore, isothiocyanates, abolished MMP-9 expression and tumor metastasis in vivo with the following efficacy: PEITC>BITC>SFN." (PMID 28969043, 2017). "Knockdown of MMP9 by shRNA significantly reduced tumor vascularization induced by fibroblasts." (PMID 28423685, 2017). "MMP9 has been demonstrated to enhance tumor cell invasion, angiogenesis and cell proliferation." (PMID 28978058, 2017). "Once in the proximity of the tumor, the macrophages release metalloproteinases, such as MMP-9." (PMID 28403223, 2017). "These cytokines cooperatively induced expression of matrix metalloproteinase MMP9 in tumor cells." (PMID 28423685, 2017). "This combination also down-regulated MMP-2, MMP-9, Shh and Gli-1 in tumor xenografts." (PMID 29157266, 2017). "Thus, our study revealed a previously unappreciated role of tumor-fibroblast interactions in stimulation of tumor vascularization, and showed an essential role of cytokine crosstalk in the cooperative up-regulation of the angiogenic driver MMP9." (PMID 28423685, 2017). "In another study, only a small sample of 49 patients was analyzed with the conclusion that MMP2 and MMP9 overexpression might be related to tumor kinetics but warrants further investigation." (PMID 29138529, 2017).
tumor (continued). "Thus, our studies reveal a previously unappreciated role of tumor-fibroblast crosstalk in stimulation of tumor vasculature by the cooperative up-regulation of the angiogenic driver MMP9 via a mechanism requiring AP1 transcription factor." (PMID 28423685, 2017). "Therefore, MMP3 likely weakly promotes tumor invasion by itself but mainly acts through activation of other MMPs, such as MMP9, in 3LL cells." (PMID 29137230, 2017). "HBEGF may contribute to tumor angiogenesis and is produced as a cell membrane-anchored protein that can be released in a soluble form by MMP9." (PMID 28977919, 2017). "Furthermore, MMP-9 is important for tumor angiogenesis by enhancing the availability of vascular endothelial cell growth factor (VEGF) in malignant tumors." (PMID 29219852, 2017). "Besides, matrix metalloproteinase (MMP)-2 (gelatinase A, 72 kDa) and MMP-9 (gelatinase B, 92 kDa) plays importantly in the process of tumor cell migration and invasion." (PMID 26848867, 2016). "Of note, NGAL and MMP-9 are molecules that are found in the tumor microenvironment." (PMID 27602581, 2016). "MMP2 and MMP9, two members of the gelatinase subfamily of MMPs, are thought to particularly play a role in the early steps of cancer cell invasion and tumor vascularization since they cleave type IV collagen, laminin and elastin, which are the major components of the basement membrane (BM)." (PMID 27042827, 2016). "Matrix metalloproteinase 9 (MMP-9) is a downstream target of Twist in tumor cells." (PMID 26762267, 2016). "Thus, together with the functional characteristics, molecular evidence suggest that combined silencing of uPA and MMP9 can reduce the tumor invasion and aggressiveness by increasing the expression of E-cadherin and reducing the mesenchymal markers." (PMID 26906973, 2016). "GAL-7 has also been reported to act as a pro-tumour protein which may be involved in the induction of matrix metalloproteinase-9 (MMP-9), which in turn plays an important role in cancer progression and metastasis." (PMID 26463353, 2016). "Moreover, the enzymatic activities of MMP-2 and MMP-9 were quantified by gelatin-zymography of the same homogenized tumour tissues." (PMID 26838095, 2016). "Overexpression of LCN2 promoted a mesenchymal-like cell morphology accompanied by increased expression of mesenchymal markers (Snail, Twist, N-cadherin, fibronectin and MMP9) that contribute to invasiveness, which accounts for their role in enhancing tumor cell motility in metastasis." (PMID 26840566, 2016). "A key role in this process is ascribed to MMP-9, which acts as a promotor of tumor invasion." (PMID 27406386, 2016). "Moreover, the inhibition of MMP-9 was reported to attenuate the invasion of tumor cells, which indicated its potential as both a cancer marker and therapeutic target." (PMID 26918342, 2016). "Blocking in the AP-1 binding activity prevents tumor promoter-induced MMP-9 transcription." (PMID 27144433, 2016). "Moreover, the DOC concentration in HNE-1 tumor was significantly higher than that in CNE-2 tumor because of the molecular targeting property of FA-CD-PLLD/DOC/MMP-9 nanocomposite." (PMID 27259274, 2016). "Proteinases such as MMP9 and PRSS2 are thought to form cascades that degrade tissue barriers and thus promote cell invasion and increased expression and secretion of these enzymes are associated with the metastatic capacity of tumor cells." (PMID 27711194, 2016). "Among the various MMPs, MMP-2 (gelatinase A) and MMP-9 (gelatinase B) may play a significant role in tumor progression and invasion in GCT." (PMID 26863138, 2016). "Tumor proliferation- and invasion-related biomarkers, including Ki67, MMP9, E-cadherin, N-cadherin, β-catenin, and Vimentin, were examined in 100 HCC primary tissue samples to determine whether NTS+NTR1+ promotes tumor invasion." (PMID 27611941, 2016).
tumor (continued). "In the past decade, many studies have demonstrated that over-expression of MMP2 and MMP9 plays a vital role in metastatic tumour cells, promoting tumour growth and angiogenesis in the tumour, thereby providing nutrition to the tumour through the newly generated vessels." (PMID 27447567, 2016). "It has also been reported that ERK1/2 could regulate expression levels of MMP2 and MMP9 in cancer cells, which can degrade extracellular matrix to promote metastasis in tumor." (PMID 26701209, 2016). "In summary, these results demonstrated that Huaier extract could inhibit the macrophages induced angiogenesis by decreasing expression of VEGF, MMP2 and MMP9, and thus inhibit the formation of new blood vessels in tumor." (PMID 26831282, 2016). "In particular, NGAL regulates the expression of MMP-9, which is responsible for several physiological and pathological processes including the enzymatic remodeling of the extracellular matrix during angiogenesis, tumor growth and metastasis." (PMID 27602581, 2016). "Our results indicated that MMP-9 activity might play a critical role in the promotion of tumor invasiveness in GCTB patients who are treated with denosumab." (PMID 26863138, 2016). "This is an exciting prospect, as it suggests that the pharmacological inhibition of uPA may suppress pro-tumor functions of both uPA and certain MMPs such as MMP9." (PMID 26956475, 2016). "Similarly, Huang and colleagues demonstrated inhibition of TNF-α-induced ICAM-1 expression along with inhibition of tumor cell (A549 cells) invasion and MMP-9 expression." (PMID 26823953, 2016). "The choice of this tumor type was based on its highly invasive and metastatic characteristics where MMP-9 overexpression may play an important role." (PMID 27115178, 2016). "Moreover, resveratrol downregulated nuclear localization of NF-κB, NF-κB phosphorylation and its acetylation, causing attenuation of NF-κB-regulated gene products (MMP-9, CXCR4) involved in tumor-invasion and metastasis." (PMID 26959057, 2016). "Additionally, they studied the expression of MMP-9 in healthy areas of the lungs in samples extracted from patients with tumours located in organs besides the lungs." (PMID 26913068, 2016). "It should be prudent to detect serum MMP-9 expression as a prognostic factor in the future, and a parallel study with a large number of subjects is needed in the future to compare the clinical significance of total expression of tissue MMP-9 and the activity of MMP-9 both in tumor tissue and serum." (PMID 26918342, 2016). "In conclusion, zingerone showed strong anti-angiogenic activity via the inhibition of MMP-2 and MMP-9 during tumor progression, suggesting that zingerone may be a potential therapeutic drug for human cancers." (PMID 27323807, 2016). "Moreover, FeDC-E NPs inhibited phosphorylation of the EGFR as well as the EGFR–ERK–NF-κB signaling pathways of the EGFR overexpressing cells along with the expression of the downstream tumor promoting proteins MMP-9 and XIAP." (PMID 27833124, 2016). "Extracellular and intracellular cleavage of N-cadherin might be involved in elevated MMP-9 expression enhancing tumor cell invasion." (PMID 27737648, 2016). "Thus, we observed expression of matrix metalloproteinases (MMP)-1, MMP-2, MMP-3, and MMP-9 mainly in the nuclei of tumor cells, while for MMP-3 and MMP-9 the immunoreactivity was also present in the cytoplasm of tumor cells and in the amyloid deposits." (PMID 27871286, 2016). "This is consistent with induction of MMP3 and MMP9 observed in eAGR2-treated non-tumor organoids." (PMID 27240165, 2016). "Additionally, in the tumor microenvironment, elevated and active MMP-9 have first to digest the outer protective shell of the NPs and make the tPApep-1lac ligands more accessible to the galectins." (PMID 27993133, 2016).
tumor (continued). "On the basis of these previous studies, indicating the major roles of the uPA and MMP9 in cancer cell progression and tumor growth, we are hypothesizing the synergistic blocking of uPA and MMP9 can reduce tumor aggressiveness and invasion." (PMID 26906973, 2016). "We next examined whether SH003 affects MMP-9 expression, as VEGF-induced tumor angiogenic vessel cells require MMP-9 to move toward a tumor mass." (PMID 27105528, 2016). "This suggests that MMP9 may also have protective effects in contrast to its role in promoting cancer cell transformation and initial tumor development." (PMID 26956475, 2016). "Equally however, the uncertainties surrounding the functions of MMP9 within the tumor microenvironment mean that inhibition of uPA may instead support cancer progression." (PMID 26956475, 2016). "The results were attributed to the targeting effect of FA-CD-PLLD, which could accumulate DOC and MMP-9 in tumor tissue and penetrate into tumor deep." (PMID 27259274, 2016). "In addition, although eventually converging at similar or even identical (mmp9) effector genes, Atp1b1a and Lgl2 can fulfill their tumor-suppressing role by blocking different pathways." (PMID 27240166, 2016). "Furthermore, LCN-2 protein overexpression was positively correlated with MMP-9 protein up-regulation in the tumor tissue and serum of LST patients (former rs = 0.631, P = 0.000; latter rs = 0.815, P = 0.000)." (PMID 27339395, 2016). "Indeed, our recent studies have shown that the induction of MMP9 by Snail occurs in ovarian A2780 cancer cells, and is able to regulate tumor neovascularization." (PMID 27029067, 2016). "In conclusion, our findings confirmed that MMP-2, MMP-7, and MMP-9 may take part in various morphological features of PDAC tumor." (PMID 27429508, 2016). "Upregulated expression of MMP2 and MMP9 may additionally support invasiveness of the motile tumor cells." (PMID 27419629, 2016). "We found that knockdown of LGMN could downregulate the expression of MMP2 and MMP9, which could break down extracellular matrix and promote tumor metastasis." (PMID 27656894, 2016). "Tumor metastasis commonly accompanied by increasing expression of MMP-9." (PMID 27578191, 2016). "Upregulation of cyclin D1, VEGF, MMP-9, miRNAs, and p21Cip1 showed a clear correlation with tumor cell cycle progression, vasculogenesis, metastasis, and invasion, and may contribute to malignant transformation of PAs to PCs." (PMID 27893664, 2016). "In addition, YAP has been confirmed to be involved in the regulation of downstream factors including CTGF, Bax, MMP-9 and CyclinD1, which are related to tumor proliferation, metastasis and angiogenesis in NSCLC and GC cells." (PMID 26921249, 2016). "Moreover, the nanoparticles suppressed the EGFR–ERK–NF-κB signaling pathways as well as the expression of the related tumor promoting proteins MMP-9 and XIAP, and subsequently inhibited the migration and invasion capabilities of cancer cells." (PMID 27833124, 2016). "Furthermore, these chemokines not only act as chemoattractants but also stimulate monocytes to express proteins that amplify monocyte recruitment and contribute to the tumor progression for example via MMP-9 secretion." (PMID 27572316, 2016). "Interestingly, gene expression profiles of tumor associated MP and MG were similar with a few exceptions like S100A8/9 and MMP9 which were down regulated in tumor MP." (PMID 27936099, 2016). "One prominent direct transcriptional target of NFκB is mmp9, a matrix-metalloprotease with collagenase activity that destabilizes basement membranes and connective tissue, thereby facilitating tumor progression and metastasis." (PMID 27240166, 2016). "Therefore, we further investigated the affect of hyperbaric oxygen on the expression of IL‐1, TNFα, and other factors including HIF‐1α, NF‐κB, VEGF, and MMP9, which were closely related to tumor development." (PMID 27734611, 2016).
tumor (continued). "According to these evidences, the analysis of cancer epigenetic modifications is the best approach to discriminate if MMP-9 overexpression is directly associated with tumor progression and not with co-morbidities or inflammatory status." (PMID 27115178, 2016). "The expression of MMP9 is also known to increase the invasion and metastasis of tumor cells." (PMID 27765919, 2016). "Moreover MMP-9 directly promotes cell migration by altering cell-cell adhesion function facilitates tumor angiogenesis and MDSCs/neutrophil recruitment by regulating the bio-availability of VEGF and its interaction with VEGFR." (PMID 27618112, 2016). "In vivo assays showed that FA-CD-PLLD/DOC/MMP-9 could inhibit HNE-1 tumor growth and decrease PCNA expression effectively." (PMID 27259274, 2016). "In summary, our study has identified and proven that infiltrated mast cells could enhance BCa metastasis via stimulating the ERβ/CCL2/CCR2/EMT/MMP9 signaling pathway in the BCa tumor microenvironment." (PMID 26556868, 2016). "MMP9 belongs to the MMP family of zinc-dependent endopeptidases that digests the extracellular matrix and has been associated with tumor cell invasion, metastasis, and tumor-induced angiogenesis." (PMID 27487154, 2016). "The classifier could not be applied to predict survival based on expression of AURKA, PTGS2 and MMP9 in the primary tumor." (PMID 26497206, 2016). "N-cadherin may enhance MMP-9 expression, thereby driving the malignant progression and invasion of tumor cells." (PMID 27737648, 2016). "Our preliminary data demonstrate that the ratio of MMP2/MMP9 activity might be a valuable prognostic marker for the response to chemotherapy that can easily be analyzed by zymography in tumor tissue samples." (PMID 26979530, 2016). "It is tempting to speculate that NACT, as induction chemotherapy, and aided by the CRT, may specifically have targeted tumor microenvironmental components with MMP9-regulated inflammatory and metastatic properties in good-prognosis patients." (PMID 27461255, 2016). "The release of MMP-2 and MMP-9 from tumor cells and surrounding cells, including endothelial cells, could enhance invasion and angiogenesis during tumor progression." (PMID 27323807, 2016). "Additionally, enforced OR3A4 expression significantly promoted VEGF-C, MMP9, and Ki-67 gene expression in the tumor tissues of nude mice." (PMID 26863570, 2016). "In ES CAV1 seems to regulate indirectly MMP-9 transcription, thus promoting tumor metastasis." (PMID 27487136, 2016). "Bergers found that MMP-9 could promote tumor angiogenesis by increasing the expression of VEGF and its receptor (VEGFR)." (PMID 27825139, 2016). "In addition, it was shown that secretion of MMP-9 by neutrophils prevents apoptosis of tumour cells and induces carcinogenesis." (PMID 27212807, 2016). "In addition, an increase in the expression level of MMP9 in all tumour samples versus healthy skin samples was observed." (PMID 26838095, 2016). "The anti-tumor effect in vivo of FA-CD-PLLD/DOC/MMP-9 was tested, and PBS was used as the control." (PMID 27259274, 2016). "It has been demonstrated that matrix metalloproteinase 9 (MMP-9) plays a crucial role in tumor angiogenesis and metastasis by turning on the angiogenic switch in avascular tumors and by mediating the development and maintenance of distinct neovascular networks sustaining tumor cell intravasation." (PMID 27975071, 2016). "NF-κB-dependent MMP-9 expression is important for endothelial cell movement toward the tumor." (PMID 26967562, 2016). "The MAPK pathways are prominent mechanisms that coordinate the transcription factors, such as NF-κB and CREB, which are activated and phosphorylated by ERK and JNK kinase systems to regulate downstream MMP-2 and MMP-9 gene expression, subsequently increase tumor initiation and progression." (PMID 27144433, 2016).